CXCL10 (C-X-C motif chemokine ligand 10)
Diseases named in the same sentence as CXCL10 in open-access papers (continued):
Sharing a sentence is not in itself a finding about the gene and the disease.
vitiligo (continued). "The skin and blood of vitiligo patients, as well as a mouse model, exhibit elevated levels of interferon-gamma and interferon-gamma-induced chemokines (CXCL9 and CXCL10)." (PMID 36475210, 2022). "Gene expression analysis of both human vitiligo skin and vitiligo mouse model skin revealed the upregulation of IFN-γ-specific signature, including chemokines CXCL10 and CXCL9, and their receptor CXCR3, which is expressed on T cells." (PMID 35432377, 2022). "A case report described a rapid regression of vitiligo that occurred in a patient treated with a potent JAK1/2 inhibitor ruxolitinib, and the reduced CXCL10 levels were observed after the treatment." (PMID 35096274, 2022). "The increased levels of some chemokines, such as CXCL10 and CXCL8, in the serum and epidermis of vitiligo have been reported in many recent studies." (PMID 35096274, 2022). "CXCL9 and CXCL10 are CXCR3 ligands that are important for the recruitment of adaptive immune cells to the skin and progression of vitiligo." (PMID 35884944, 2022). "Most studies on vitiligo have focused on active disease, and the importance of the CXCL9/CXCL10/CXCR3 axis is well established from studies on human skin samples." (PMID 35653192, 2022). "Multiple monoclonal antibodies are available for vitiligo treatment, targeting IFN-γ, CXCL10, CXCR3, HSP70i, IL-15, IL-17/23, and TNF." (PMID 36119071, 2022). "Recently, the importance of the Th1-type immune response in the pathogenesis of vitiligo, as well as the C-X-C Motif Receptor 3 (CXCR3) and its corresponding chemokine, CXCL10, was highlighted." (PMID 36556267, 2022). "High levels of CXC chemokines induced by IFN - γ such as CXCL9, CXCL10 and CXCL11 were also found in patient serum, being the most highly expressed genes in the transcriptional profile of skin lesions from vitiligo patients." (PMID 34858164, 2021). "The interaction between CXCL10 and its receptor on autoreactive T cells, CXCR3, is involved in the maintenance of depigmentation in vitiligo and the expression of CXCL10 correlates with the severity of the disease." (PMID 34768860, 2021). "In conclusion, the activity of vitiligo has a positive correlation with the levels of CXCL9 and CXCL10 in the blister fluid." (PMID 34521889, 2021). "We found significant upregulation of CCL5 and CXCL10, as well as CXCL7 (gene name PPBP) in canine VKH and vitiligo." (PMID 33384688, 2020). "To confirm that IFNG and CXCL10, two well-characterized drivers of anti-melanocyte responses, are expressed at the protein level in lesional skin of VKH and vitiligo canines, we performed immunohistochemistry." (PMID 33384688, 2020). "In dogs, we found enrichment of T cell gene signatures, with upregulation of IFNG, TNF, PRF1, IL15, CTSW, CXCL10, and CCL5 in both VKH and vitiligo in dogs compared to healthy controls." (PMID 33384688, 2020). "These include CXCL9, CXCL10, and CXCL11 and its receptor CXCR3, both in peripheral cells of the immune system and in the skin of patients diagnosed with vitiligo." (PMID 32992956, 2020). "However, as high amounts of CXCL10 characterize vitiligo in an active phase, there is the possibility that the reported differences among immunotherapy-induced leukoderma and vitiligo could be less significant when only vitiligo patients in an active phase of the disease are included." (PMID 31731645, 2019). "Stimulation of healthy or vitiligo melanocytes with IFNγ induced a significant increase in mRNA expression of CXCL4, CXCL9, CXCL10 and CXCL11." (PMID 31097717, 2019). "Our results showed that, except for IL-15, the levels of these factors were significantly higher in recurrent patients compared to persistent stable patients, which suggest that increased levels of IFN-γ, CXCL9, CXCL10, CXCL11 and IL-6 are potential triggers for vitiligo recurrence." (PMID 39981245, 2025).
vitiligo (continued). "In patients with vitiligo, excessive accumulation of KYNA may induce the expression of CXCL10 in keratinocytes through activation of the AhR pathway, which contributes to the recruitment of CD8 + T cells at the site of lesions." (PMID 40703229, 2025). "In contrast, vitiligo model mice showed a marked upregulation of CXCL9 and 10: CXCL9 MFI increased to 3910 ± 62.39 (epidermis) and 3018 ± 157.8 (dermis), and CXCL10 MFI similarly rose to 3868 ± 331.9 (epidermis) and 3927 ± 329 (dermis) relative to normal controls." (PMID 40725033, 2025). "Notably, both classic vitiligo and drug-induced VLD share key immunologic features, including IFN-γ/CXCL10-mediated chemotaxis and the involvement of tissue-resident memory T cells and melanocyte-specific CD8+ T cells." (PMID 40861456, 2025). "Based on previous research, we propose a hypothesis that IFN-γ, CXCL9, CXCL10, CXCL11, IL-6, and IL-15 are involved in the recurrence of vitiligo and are interconnected." (PMID 39981245, 2025). "We hypothesize that in vitiligo, IRF3 might contribute to the development of the condition by promoting the release of CXCL10." (PMID 38660673, 2024). "The IFN-γ/JAK/STAT/CXCL10 pathway has been proved to be related to the occurrence and development of vitiligo, and the role of EGCG in modulating immunity and downregulating inflammatory factors may be accomplished by intervening IFN-γ/JAK/STAT/CXCL10 pathway." (PMID 39119340, 2024). "A gene expression analysis of vitiligo lesions has indicated significant upregulation of the expression levels of IFN-γ-induced genes, including the T-cell chemokine receptor CXCR3 and its multi ligands CXCL9 and CXCL10." (PMID 39338414, 2024). "CD8+ T lymphocyte toxicity is also an important component of vitiligo pathogenesis, therefore therapies blocking IFN-γ, the IFN-γ receptor, the ligands CXCL10 and CXCL9 and the receptor CXCR3 may also be worth exploring and testing in clinical studies." (PMID 37298700, 2023). "However, the levels of IFNG, PRF1, GZMB and CXCR3, CXCL9, CXCL10, CXCL12, and other cytokines also had an upward trend in the vitiligo group." (PMID 37207234, 2023). "Gene expression analysis of vitiligo lesions showed that interferon-γ (IFN-γ) and IFN-γ-induced genes, including T-cell chemokine receptor CXCR3 and its multiple ligands, such as CXCL9 and CXCL10 were significantly upregulated." (PMID 37207234, 2023). "Therapies that disrupt the pathway targeting IFN-γ, the IFN-γ receptor, the downstream signal JAK-STAT pathway, CXCL10 and its receptor CXCR3 have been some of the most promising in vitiligo management and may become the first to be approved." (PMID 37298700, 2023). "Activation of apoptosis triggered by the Fas/Fas ligand interaction can be mediated by molecules which are involved in the pathology of vitiligo including CD8+ T cells, the TNF-α/TNR receptor (TNFR) pathway, the IFN-γ signaling pathway, and the CXCL10/CXCR3B pathway." (PMID 36980277, 2023). "Indeed, HSP70i is the core participant in vitiligo predominantly through ﻿HSP70i-plasmacytoid dendritic cells (pDCs)-IFN-α-CXCL9 and CXCL10-cytotoxic T lymphocyte (CTL) axis." (PMID 36119071, 2022). "Furthermore, a positive correlation has been revealed between CXCL10, a mediator of the immune response and a chemoattractant for CD8+ T cells, and H2O2 levels in vitiligo lesions." (PMID 35329832, 2022). "Research is in progress to investigate the important cytokines involved in the pathogenesis of vitiligo, including IFN-γ, CXCL10, CXCR3, HSP70i, IL-15, IL-17/23, and TNF, the blockade of which has undergone preliminary attempts in animal models and some patients." (PMID 36119071, 2022). "On the other hand, inhibition of CXCR3 was reported to prevent the CXCL10-induced melanocyte apoptosis and T cell infiltration in the skin, and blocking their receptor CXCR3 by CXCR3 antibodies led to repigmentation in mice with established vitiligo." (PMID 35096274, 2022).
vitiligo (continued). "However, since keratinocytes are abundant in the skin, they produced the bulk of CXCL10, and were predominantly responsible for MSA-specific CD8+ T cell recruitment in vitiligo." (PMID 35432377, 2022). "IFN-γ signature chemokines, CXCL9 and CXCL10, are highly expressed in both lesion skin and non-lesion skin of vitiligo patients compared to healthy control with statistical significance." (PMID 35464413, 2022). "Intriguingly, of the mentioned cytokines and chemokines, many are reported to be biomarkers for vitiligo like IL‐1β, CXCL9, CXCL10, and CXCL16, which might aid vitiligo diagnosis and prognosis." (PMID 33200838, 2021). "In non-lesional skin of active vitiligo patients, CXCL10 has been found at higher levels, as well as both CXCL9 and CXCL10 mRNA by immunohistochemistry." (PMID 34445526, 2021). "In addition, CXCL10 recruits T cells within the skin through the CXCR3 receptor, which prolongs and exacerbates the established vitiligo lesion." (PMID 34868078, 2021). "Non-stimulated vitiligo melanocytes had significantly higher baseline (or constitutive) production of CXCL10 compared to healthy melanocytes." (PMID 31097717, 2019). "To assess the role of apoptosis in CXCL10-induced melanocyte death, in parallel we have shown cleavage of caspase-3 in vitiligo patients but not in healthy controls and this effect to be reversed by QVd-OPh, a caspase inhibitor." (PMID 31097717, 2019). "Interestingly, in vitiligo an IFN-γ signature is present and high serum levels of CXCL-9 or, more prominently, of CXCL-10 are present in patients with progressive disease." (PMID 31731645, 2019). "However, addition of pre-stressed NKs or ILCs from vitiligo patients dramatically increased their own melanocyte production of CXCL9, CXCL10, CXCL11 and IFNγ." (PMID 31097717, 2019). "Indeed, the tissue-resident memory T (Trm) cells in vitiligo skin express CXCR3, the receptor for CXCL10, and are prone to IFN-γ production." (PMID 30515176, 2018). "Highly induced CXCL10 and CXCR3 were found in vitiligo patients." (PMID 29456788, 2017). "In the context of Th17 inhibition, the Th1 immune response may be relatively active due to lack of regulation, thereby enhancing the activation of the IFN-γ/CXCL10 axis, promoting CXCR3+ CD8+ T cell recruitment and melanocyte destruction, and inducing or aggravating vitiligo." (PMID 40861456, 2025). "In addition, the pro-inflammatory factor IFN-γ released by CD8+ T cells induces the production of chemokines, including the C-X-C motif chemokine ligands 9 and 10 (CXCL9 and CXCL10), which in turn promote the recruitment of CD8+ T cells to melanocytes and exacerbate the progression of vitiligo." (PMID 40725033, 2025). "However, higher amounts of CXCL10 were found in active vitiligo, suggesting that reported differences between ICI-induced DAL and active vitiligo could be less significant." (PMID 39421737, 2024). "Additionally, CXCL10, an IFN-γ-specific signature, is sufficient to initiate and maintain depigmentation via the activation of autoreactive CXCR3+ CD8+ T lymphocytes in this vitiligo mouse model." (PMID 38673994, 2024). "For example, CXCL9 and CXCL10 induced by IFN-γ play a key role in the skin migration of CD8+ T cells in vitiligo, and the expression of CXCR3 on melanocyte-specific CD8+ T cells has been detected in skin lesions and in the peripheral blood of vitiligo patients." (PMID 33679890, 2021). "A central role of keratinocytes in vitiligo has recently emerged, as it is well documented that they are damaged and that these cells represent the predominant source of chemokines, such as CXCL9 and CXCL10, involved in the recruitment of T cells to vitiligo skin." (PMID 33126704, 2020). "In addition to CXCL10, IFN-induced IFIH1 was upregulated in vitiligo skin in the current study." (PMID 30515176, 2018).
vitiligo (continued). "Therefore, we would expect to detect a majority of chemokines (e.g. CXCL10, CXCL11) and cytokines (e.g. IL-17, IL-23) being differentially expressed across the different publications when comparing vitiligo patients to healthy controls or active vs stable vitiligo patients." (PMID 38715599, 2024). "Interestingly, CXCL10 could not be detected in this study, despite it already being reported in numerous publications to be significantly elevated in vitiligo patients compared to healthy controls." (PMID 38715599, 2024). "IFN-γ, CXCL9, CXCL10, CXCL11, IL-6, and IL-15 were expressed at higher levels in the circulation of patients with both segmental and non-segmental vitiligo compared to healthy controls (p < 0.001)." (PMID 39981245, 2025). "The results of a comparative study indicate that CXCL10 and IFN mRNA expression was notably elevated in non-lesional and perilesional skin in patients with vitiligo compared to healthy controls." (PMID 39201060, 2024). "CXCL10 is elevated substantially with active vitiligo compared to stable vitiligo, whereas CXCL9 of active vitiligo is significantly elevated compared to healthy controls but not stable vitiligo." (PMID 35464413, 2022).
Obesity (80 papers, 2010 to 2026). Accumulation of substantial excess body fat. "Because plasma CXCL10 expression was found to be elevated in patients with obesity, we next wanted to validate the association of plasma CXCL10 and alterations of circulating monocytes." (PMID 38175171, 2024). "Previously, we and others reported that the increased adipose expression of CXCL10 in individuals with obesity was associated with inflammatory (IL-1β expression, C-reactive protein levels) and other factors (BMI, CXCR3, and reduced neovascularization causing adipose tissue hypoxia)." (PMID 39065674, 2024). "Elevated circulating levels of CXCL10 in obese patients are associated with obesity markers and may be involved in insulin resistance and obesity-related cardiovascular complications." (PMID 39334887, 2024). "CXCL10 (IP-10) plays a key role in leukocyte homing to the inflamed tissues and its increased levels are associated with the pathophysiology of various inflammatory diseases including obesity and type 2 diabetes." (PMID 39065674, 2024). "CXC chemokines (including CXCL16/CXCR6, CXCL10, and CXCL12/CXCR4) influence inflammation linked to obesity and affect immune cell migration, tumor development, and metabolic processes." (PMID 41227378, 2025). "Data revealed significantly elevated plasma CXCL10 in patients with obesity with an additive effect of OSAS." (PMID 38175171, 2024). "This research project aims to investigate the impact of CXCL10 on human monocytes in patients with obesity." (PMID 38175171, 2024). "In the present study, we analyzed the impact of CXCL10 on circulating CD14/CD16 monocyte subsets from 92 patients with obesity and/or OSAS as well as on THP-1 monocytic cells." (PMID 38175171, 2024). "We detected significantly increased plasma levels of chemokine CXCL10 in patients with obesity compared with healthy donors using ELISA measurements." (PMID 38175171, 2024). "Chemokine CXCL10 is an important regulator of proinflammatory immune responses and is significantly increased in patients with severe obesity." (PMID 38175171, 2024). "Our data show, for the first time, to our knowledge, that CX3CR1 is involved in alternative CXCL10 signaling in human monocytes in obesity-related inflammation." (PMID 38175171, 2024). "Physical activity, as part of an integrated lifestyle, is effective in reducing levels of the chemokine IP10/CXCL10 in the immune system, thus potentially helping to alleviate obesity-related immunometabolic problems." (PMID 39334887, 2024). "This correlation is characterized by an elevation in mRNA levels of IL-6, IL-12, IFN, and CXCL10 chemokines in individuals with obesity." (PMID 38024342, 2023). "In the high-fat diet-induced obesity mouse model, CXCL10 expression in skeletal muscle is increased, and the capillary density is decreased, while after aerobic training, CXCL10 expression is reduced, and the capillary density is increased." (PMID 36091401, 2022). "Several reports have suggested the role of other chemotactic factors in obesity-induced macrophage infiltration and IR, including CXCL-10 or interferon-γ-inducible protein 10 (IP-10), which is a potent chemoattractant for various leukocyte subsets." (PMID 31627295, 2019). "Patients with obesity have been noted to have increased circulating levels of the CXCL10 chemokine." (PMID 41227378, 2025). "In addition to these cytokines, individuals with obesity can also present higher circulating levels of IP-10 (also known an CXCL10), a chemokine involved in the recruitment of immune cells to sites of inflammation." (PMID 39125408, 2024). "However, the immunological consequences of plasma CXCL10 in patients with obesity in terms of peripheral blood monocytes are poorly understood." (PMID 38175171, 2024). "In patients with obesity, elevated circulating levels of the CXCL10 chemokine have been observed." (PMID 39334887, 2024).